ATP6V1C2 (ATPase H+ transporting V1 subunit C2)
Description:
Subunit of the V1 complex of vacuolar(H+)-ATPase (V-ATPase), a multisubunit enzyme composed of a peripheral complex (V1) that hydrolyzes ATP and a membrane integral complex (V0) that translocates protons (By similarity). V-ATPase is responsible for acidifying and maintaining the pH of intracellular compartments and in some cell types, is targeted to the plasma membrane, where it is responsible for acidifying the extracellular environment (By similarity). Subunit C is necessary for the assembly of the catalytic sector of the enzyme and is likely to have a specific function in its catalytic activity (By similarity).
Synonyms: VMA5; ATP6C2
Tractability: No criterion of Open Targets' tractability assessment is met for any kind of drug.
Gene: Protein-coding gene on chromosome 2 (10,721,100 to 10,785,110, forward strand). Ensembl gene ENSG00000143882.
Subcellular location (Human Protein Atlas): Mitochondria
Pathways (Reactome):
Transport of small molecules: Ion channel transport; Transferrin endocytosis and recycling
Cellular responses to stimuli: Amino acids regulate mTORC1
Immune System: ROS and RNS production in phagocytes
Signal Transduction: Insulin receptor recycling
Gene Ontology:
Molecular function: identical protein binding; proton-transporting ATPase activity, rotational mechanism; proton transmembrane transporter activity
Biological process: positive regulation of Wnt signaling pathway; regulation of macroautophagy; proton transmembrane transport
Cellular component: extracellular exosome; lysosomal membrane; cytosol; proton-transporting V-type ATPase, V1 domain
Genetic constraint (gnomAD): Loss-of-function variants: 40 observed, 51.44 expected, observed/expected ratio (o/e) 0.78, 90% interval 0.6 to 1.01. The upper end of that interval is the gene's LOEUF score, 1.01, which puts it in group 4 of 6, group 1 being the genes least tolerant of losing a copy. Missense variants: 423 observed, 493.92 expected, observed/expected ratio (o/e) 0.86, 90% interval 0.79 to 0.93. Synonymous variants: 206 observed, 189.48 expected, observed/expected ratio (o/e) 1.09, 90% interval 0.97 to 1.22.
Homologues: Orthologues: chimpanzee ATP6V1C2 (99% identical), macaque ATP6V1C2 (98% identical), dog ATP6V1C2 (95% identical), pig ATP6V1C2 (94% identical), rabbit ATP6V1C2 (93% identical), rat Atp6v1c2 (92% identical), guinea pig ATP6V1C2 (87% identical), mouse Atp6v1c2 (83% identical), tropical clawed frog atp6v1c2 (64% identical), Drosophila melanogaster Vha44 (51% identical), zebrafish atp6v1c2 (45% identical), Caenorhabditis elegans vha-11 (44% identical). Paralogues in human: ATP6V1C1 (56% identical).
Diseases named in the same sentence as ATP6V1C2 in open-access papers:
ATP6V1C2 is named in the same sentence as 19 diseases in open-access papers, as found by Europe PMC text mining. Sharing a sentence is not in itself a finding about the gene and the disease. The quoted sentences say what the papers report.
breast carcinoma (3 papers, 2014 to 2022). "ATP6V1C2 encodes ATPase H+ transporting V1 subunit C2, which has been documented to be involved in renal clear cell carcinoma (RCC) other than breast cancer (BC)." (PMID 36212133, 2022). "For comparison, other V-ATPase subunits, ATP6v1c2 or ATP6v0a3/TCIRG1, are only overexpressed or genomically amplified in 7% of breast cancers, respectively, and their overexpression or genomic amplification didn't significantly correspond with effects on patient survival." (PMID 28504970, 2017).
colon adenocarcinoma (2 papers, 2022 to 2024). "In a colon adenocarcinoma study, ATP6V1C2 knock-down (KD) affected WNT pathway-related genes and epithelial-to-mesenchymal transition (EMT)-related genes, with a decrease in fibronectin-1, vimentin and increase in E-Cadherin, thus attenuating metastasis." (PMID 39696035, 2024).
colorectal cancer (2 papers, 2023 to 2025). A primary or metastatic malignant neoplasm that affects the colon or rectum. "For example, ATP6V1C2 has been demonstrated to promote or inhibit tumour proliferation in oesophageal cancer, colorectal cancer and renal clear cell carcinoma." (PMID 40016789, 2025). "Top statistically significant hits included ADAMTS5, ATP6V1C2, and S100A6—genes that have been previously identified as biomarkers for colorectal cancer." (PMID 37138315, 2023).
esophageal carcinoma (2 papers, 2022 to 2025). A primary or metastatic malignant neoplasm involving the esophagus. "ATP6V1C2 as a family member has been documented to associate with esophageal carcinoma and renal clear cell carcinoma, while its roles in COAD remain elusive." (PMID 36212133, 2022).
amelogenesis imperfecta (1 paper, 2021). Amelogenesis imperfecta (AI) represents a group of developmental conditions affecting the structure and clinical appearance of the enamel of all or nearly all the teeth in a more or less equal manner, and which may be associated with morphologic or biochemical changes elsewhere in the body. "This approach has allowed to establish ATP6V1C2 as a novel recessive dRTA gene in humans and has confirmed the phenotypic expansion of recessive WDR72 mutations from isolated amelogenesis imperfecta to syndromic amelogenesis imperfecta with dRTA." (PMID 33770395, 2021).
breast tumors (1 paper, 2017). "We began by checking the human genomics data to find that ATP6v1c1 is a highly amplified and overexpressed V-ATPase subunit in breast tumors relative to other V-ATPase subunits, such as Atp6v1c2 and Atp6v0a3." (PMID 28504970, 2017).
colorectal adenocarcinoma (1 paper, 2025). The most common type of colorectal carcinoma. "In colorectal adenocarcinoma, elevated expression of ATP6V1C2 correlates with a poor prognosis, potentially via the activation of the Wnt signaling pathway and the facilitation of epithelial-mesenchymal transition." (PMID 40463372, 2025).
Encephalopathy (1 paper, 2022). Encephalopathy is a term that means brain disease, damage, or malfunction. "Further, silencing of miRNA-485-5p resulted in a significant increase in the expression of the target gene, ATP6V1C2, levels of which were 4.121-fold higher in infants with SAE than that in preterm infants without encephalopathy after sepsis (p < 0.05)." (PMID 35689189, 2022).
esophageal squamous cell carcinoma (1 paper, 2025). Esophageal squamous cell carcinoma (ESCC) is a type of esophageal carcinoma (EC) that can affect any part of the esophagus, but is usually located in the upper or middle third. "In esophageal squamous cell carcinoma, an increased ATP6V1C1 to ATP6V1C2 ratio, reflecting the upregulation of ATP6V1C1 and downregulation of ATP6V1C2, has been identified as a distinctive molecular characteristic of the disease." (PMID 40463372, 2025).
viral infection (1 paper, 2024). "Transcriptomic analysis reveals upregulation of genes associated with viral infection and downregulation of genes involved in neural function maintenance, such as the ATP6V1C2 gene." (PMID 38711616, 2024). "Transcriptomic analysis of MNs revealed upregulated genes associated with viral infection and a downregulation of genes related to the maintenance of neural function, such as the ATP6V1C2 gene." (PMID 38711616, 2024).
cancer (5 papers, 2020 to 2025). A tumor composed of atypical neoplastic, often pleomorphic cells that invade other tissues. "The previous and our studies suggest that ATP6V1C2 displays distinct expression status, and prognostic role among different cancers and the molecular mechanisms of ATP6V1C2 related to COAD, RCC, and BC are different." (PMID 36212133, 2022). "In the external validation set, ATP6V1C2 did not exhibit significant differences in expression between the normal and cancer groups." (PMID 40463372, 2025). "Our study suggests that overexpressed ATP6V1C2 might promote EMT by activating Wnt signaling pathway, resulting in cancer metastasis and poor prognosis." (PMID 36212133, 2022).
tumor (5 papers, 2022 to 2025). "We also found that high expression of ATP6V1C2 could decrease pathway activity of CD8 T effector implicated in tumor microenvironment (TME)." (PMID 36212133, 2022). "For example, involved in both tumor progression and metastasis, ATP6V1C2 functions in the biological process of transferring hydrogen ions." (PMID 36765702, 2023). "However, the model requires further refinement, particularly in elucidating the underlying biological mechanisms of ATP6V1C2, SRPX, and NT5E to better comprehend their roles in tumor progression and patient prognosis." (PMID 40463372, 2025).
ATP6V1C2 also shares sentences with these, for which no sentence is quoted: renal clear cell carcinoma (2 papers); asthma (1); breast invasive carcinoma (1); infection (1); lung adenocarcinoma (1); rheumatoid arthritis (1); Sepsis (1).